APOE (apolipoprotein E)
Diseases named in the same sentence as APOE in open-access papers (continued):
Sharing a sentence is not in itself a finding about the gene and the disease.
endothelial dysfunction (continued). "No sign of intraluminal plaques was observed in cerebral blood vessels in our study, which is in line with a report showing increased oxidative stress and endothelial dysfunction in cerebral arterioles in high-fat fed ApoE−/− mice, but in the absence of atherosclerotic lesions." (PMID 21356305, 2011). "The present study found that ACh-induced endothelial dysfunction in ApoE KO mice was ameliorated by Tudca, the ER stress inhibitor, and Tunicamycin, the ER stress inducer, directly impaired endothelium-dependent vasodilation in the WT and ApoE KO-EX mice, but not in ApoE KO mice." (PMID 29784903, 2018). "One possible explanation might be that the endothelial damage in the present ApoE knockout mouse model is already so pronounced and that endothelial CB2 activation has little or no further impact on endothelial dysfunction." (PMID 36178662, 2023). "Interestingly, NOX4 protein expression was upregulated in the media, but not in the endothelium of the ApoE−/− mouse aorta, suggesting that NOX4 did not contribute to endothelial dysfunction." (PMID 37873768, 2023). "Also, immunoreactivity to LOX-1 and NOX2, but not to NOX1 or NOX4 was elevated in retinal vessels of ApoE-/- mice, suggesting that a mechanism involving LOX-1, NOX2, and ROS may be involved in mediating endothelial dysfunction." (PMID 31781340, 2019).
Insulin resistance (185 papers, 2006 to 2026). Increased resistance towards insulin, that is, diminished effectiveness of insulin in reducing blood glucose levels. "Second, this study highlights the need to evaluate insulin resistance and prediabetic status in patients with AD, in order to possibly include treatment of this relevant risk factor, particularly in APOE ε4 carriers." (PMID 39992249, 2025). "One trial specifically included participants with MCI who also had concomitant type 2 diabetes (T2D) or insulin resistance, while 2 studies adopted a precision medicine approach by enriching their study populations with individuals carrying the APOE-ε4 allele." (PMID 41145344, 2025). "Previous studies found, however, an increased risk of insulin resistance in APOE (ε4/ε4) persons, exercising a synergetic interaction on the alteration of brain-blood barrier integrity." (PMID 40606939, 2025). "Key factors include environmental influences, age, lifestyle, and biological factors such as apolipoprotein E (ApoE) variants, insomnia, insulin resistance, and alterations in gut microbiota." (PMID 39274904, 2024). "The apolipoprotein E4 (APOE4) gene variant is the strongest genetic risk factor for AD, and it has been demonstrated that ApoE4 interferes with IR signaling, suggesting a role for ApoE4 in association with insulin resistance in the pathogenesis of AD." (PMID 37445790, 2023). "In asymptomatic APOE ε4 carriers, increased systemic insulin resistance is associated with higher tau phosphorylation." (PMID 36372924, 2023). "PPARα-null mice were protected against HFD-induced insulin resistance, and PPARα deficiency reduced insulin resistance in apoE-null mice." (PMID 35655996, 2022). "ApoE genotype has been linked to the development of peripheral insulin resistance, particularly when challenged with risk factors." (PMID 35884888, 2022). "STZ injection caused hyperglycemia and insulin resistance in the ApoE-/- mice indicating the successful induction of T2D." (PMID 36286043, 2022). "Insulin resistance and apolipoprotein E (apoE) are also linked with oxidative stress and can impact the BBB." (PMID 34829566, 2021). "The Metabolic Syndrome, reflecting systemic insulin resistance in conjunction with lipid and cardiac co-morbidities, also is associated with AD, independently of the APOE genotype." (PMID 34220427, 2021). "In subjects with family history of AD, higher insulin resistance has been associated with reduced cerebral glucose metabolism, as well as changes in CSF Aβ and tau and worse memory performance, especially in APOE e4 carriers." (PMID 33597002, 2021). "Previous studies have shown that ApoE is not only important for fat accumulation, but is also linked with mechanisms of insulin resistance and the development of the metabolic syndrome." (PMID 32514005, 2020). "Glucose homeostasis, lipids and arterial blood pressure in mice with endothelium-specific insulin resistance deficient in apolipoprotein E and Nox2 (ESMIRO/ApoE−/−/Nox2−/y)." (PMID 32401607, 2020). "We also observed that ApoE deficiency induced insulin resistance in the hippocampus and cortex of mice based on levels of p-IRS, which is phosphorylated by JNK in response to ER stress." (PMID 27809235, 2016). "ApoE, a protein with potent anti-atherogenic action has reduced pulmonary expression in PAH patients and experimental evidence indicates that ApoE-deficient mice fed a high fat diet exhibit features of insulin resistance." (PMID 29552090, 2014). "Taken these together, increased oxidative stress in hyperglycemia and reduced lipid clearance because of apoE gene polymorphism are effective in developing insulin resistance and T2DM." (PMID 22520940, 2012). "The combination of HFD, ApoE deficiency, and hypoadiponectinemia resulted in an additive effect on insulin resistance." (PMID 23152772, 2012).
Insulin resistance (continued). "This could signify that clinically well APOE E2 individuals exhibit a signature similar to insulin resistance as compared to E3, which may be supported by APOE E2’s association with increased DAGs, especially in older individuals, discussed earlier." (PMID 40323280, 2025). "This study explored whether similar compensatory mechanisms are active in APOE ε4 carriers and individuals with elevated insulin resistance, both susceptible to entorhinal cortex dysfunction." (PMID 39656485, 2024). "This can be explained by the fact that conditions such as hyperglycaemia, hyperinsulinaemia, insulin resistance, as well as the presence of APOE ε4 allele, could strongly induces the formation of senile plaques in DM patients." (PMID 36372924, 2023). "As the development of insulin resistance, both in the periphery and the CNS, can involve inflammation, as will be discussed in more detail later, apoE pools could also be implicated in this process." (PMID 35884888, 2022). "In asymptomatic APOE e4 carriers, insulin resistance has been associated with higher CSF levels of tau, suggesting that insulin resistance might contribute to neurodegeneration." (PMID 33597002, 2021). "Apolipoprotein E (apoE) is one protein linked to insulin resistance, oxidative stress, and AD." (PMID 34829566, 2021). "Third, treating mice, which are both deficient in ApoE and display endothelium-specific insulin resistance, with the Nox2-specific inhibitor gp91dstat reduced superoxide generation and deposition of lipid in the thoraco-abdominal aorta without elastin fragmentation or increasing ICAM-1 expression." (PMID 32401607, 2020). "In the present study, we employed a model of APOE-targeted replacement mice and high-fat diet (HFD)-induced insulin resistance to investigate diabetic mechanisms associated with apoE4 pathology and the extent to which they are driven by peripheral and central processes." (PMID 32075060, 2020). "Similarly, TRAIL deficiency leads to insulin resistance as the result of the significant impairment of β-cell function and marked islet macrophage infiltration in ApoE/TRAIL-knockout mice fed with a high-fat diet." (PMID 29056829, 2017). "Here, we show that TRAIL-deficiency in ApoE-/- mice exacerbates nephropathy and insulin resistance." (PMID 24667560, 2014). "A study of mice with a heterozygous ATM mutation and apolipoprotein E deficiency, involved in the redistribution of triglycerides and cholesterol in different tissues, showed accelerated progression of atherosclerotic lesions in association with insulin resistance and glucose intolerance." (PMID 40597142, 2025). "This study aimed to investigate whether carriers of the APOE ε4 allele and individuals with elevated peripheral insulin resistance exhibit similar impairments in PI and how brain network specialization during the resting state modulates the impact of these AD risk factors on PI processes." (PMID 39656485, 2024). "However, there was a trend between APOE genotype and decreasing insulin sensitivity index (Si) in the order E2 > E3/E3 > E4 (p = 0.09), which is consistent with E4 carriage being associated with relatively greater insulin resistance than its counterparts." (PMID 30336580, 2018). "However, whether the combination of HFD, ApoE deficiency, and hypoadiponectinemia has an additive effect on insulin resistance is unknown." (PMID 23152772, 2012). "We examined effects of insulin resistance and APOE genotype on blood–brain barrier (BBB) integrity in AD." (PMID 39992249, 2025). "Our results provide an atlas for intervention targets to potentially reduce AD risk and promote longevity, and further contextualize the complex relationship between APOE, biological aging, and insulin resistance." (PMID 40323280, 2025).
Insulin resistance (continued). "BMI correlated positively with APCS (r = 0.52, p = 0.003) and apoE (r = 0.44, p = 0.02) in PCOS women; Homeostasis model of assessment–insulin resistance (HOMA-IR) correlated positively with apoE (r = 0.37, p = 0.04) in PCOS women." (PMID 38397086, 2024). "In apolipoprotein E-deficient mice, DSF improved insulin resistance, prevented histological changes in mesenteric adipose tissue, tissue inflammation, steatohepatitis, and reduced the extent of aortic plaques." (PMID 38474087, 2024). "The results of the present study suggest that the APOE ɛ4 genotype and insulin resistance influence PI performance through different large-scale network mechanisms." (PMID 39656485, 2024). "Emerging evidence suggests that ApoE also participates in energy metabolism, potentially as a molecular link connecting adipose tissue and insulin resistance (IR)." (PMID 38062308, 2023). "Numerous metabolic alterations, such as insulin resistance, low plasma adiponectin levels, and reduced expression of apolipoprotein E, have been proposed to induce PAH in an animal model." (PMID 37443009, 2023). "As expected, FA supplementation decreased hepatic lipid accumulation and improved the hepatic insulin resistance, which was consistent with a previous study using ApoE−/− mice and rats." (PMID 35745260, 2022). "Taken together, altered glucose metabolism, insulin resistance and APOE ε4 genotype seem to interact and promote an AD-like phenotype, especially in the hippocampus." (PMID 35418601, 2022). "Increased circulating levels of lipoprotein-A, apolipoprotein-A1, and apolipoprotein-E as a result of insulin resistance in acromegaly leads to disorders of lipoprotein metabolism." (PMID 33389987, 2021). "Utilizing this model, we investigated the effects of the APOE genotype and HFD on glucose metabolism and insulin resistance, and the extent to which these are associated with apoE4-driven peripheral or central pathologies." (PMID 32075060, 2020). "The present study examined the effects of the APOE genotype and HFD on glucose metabolism and insulin resistance, and the extent to which they are associated with peripheral and central pathologies." (PMID 32075060, 2020). "Male apoE−/− mice not only displayed insulin resistance under HFD-feeding, but also developed higher RVSP along with RV hypertrophy and increased muscularization of small pulmonary arteries." (PMID 30813929, 2019). "Another key finding in the present study was the variation in insulin resistance according to APOE genotype and plasma total SFA; nutrient-gene interactions were observed for both HOMA-IR and insulin." (PMID 28740125, 2017). "Stearoyl-CoA desaturase-1 that catalyses oleic acid synthesis and is associated with insulin resistance was increased in visceral adipose tissue and cholesterol efflux components (ABCA1, apoE) were decreased in subcutaneous and liver tissue." (PMID 27488580, 2016). "We investigated the effects of genistein supplementation on peripheral and central insulin resistance in WT mice and ApoE−/− mice." (PMID 27809235, 2016). "Abnormal fasting glucose levels, reflecting insulin resistance, are an important pathophysiological characteristic for the development of human NASH, which were found in ApoE-deficient mice after seven weeks of WD." (PMID 26263022, 2015). "Compared with ApoE-/- mice, TRAIL-/-ApoE-/- mice displayed insulin resistance and type-2 diabetic features with reduced renal insulin-receptor expression." (PMID 24667560, 2014). "In serum, glucose and insulin concentrations were dramatically upregulated compare to wild type mice, indicating that apoE knock-out resulted in glucose uptake impairment and insulin resistance (IR)." (PMID 24526524, 2014).
Insulin resistance (continued). "In the present study, we show the first demonstration that TRAIL-gene deletion in HFD-fed ApoE-/- mice results in accelerated nephropathy and insulin resistance." (PMID 24667560, 2014). "Our study analyzed the effects of miR-492 on insulin resistance, endothelial activation, and resistin expression in apoE knock-out mice and human umbilical vein endothelial cells after high-glucose treatment and miR-492 mimics transfection." (PMID 24526524, 2014). "This coincides with the development of insulin resistance in WAT of APOE*3Leiden mice under the experimental conditions employed herein." (PMID 24086498, 2013). "In the current study, we investigated the impact of liraglutide on insulin resistance induced by the combination of HFD, ApoE deficiency and adiponectin knockdown in vivo." (PMID 23152772, 2012). "New findings of this work were the changes of FGF-21 and its receptors in a new animal model where insulin resistance was induced by the combination of HFD, ApoE deficiency and adiponectin knockdown." (PMID 23152772, 2012). "ApoE−/− mice per se develop biochemical features of insulin resistance, lipid abnormalities and liver steatosis but fail to develop NASH like features unless they are feed an high fat diet." (PMID 23029000, 2012). "Our study results show that high-fructose-induced insulin resistance promotes a proinflammatory and prooxidant state which accelerates atherosclerotic plaque formation in ApoE-KO mice." (PMID 22474431, 2012). "HFD-fed ApoE−/− mice were treated with adenovirus vectors expressing shAcrp30 to produce insulin resistance." (PMID 23152772, 2012). "The ApoE-/- mice are generated on a C57BL/6 background, and this model is highly susceptible to cardiovascular disease, overweight, insulin resistance, and the development of metabolic syndrome." (PMID 21745393, 2011). "Insulin resistance was induced by feeding APOE mice a high (60%) fat diet (HFD), or low (10%) fat diet (LFD) for 32 weeks." (PMID 21347323, 2011). "Furthermore, we explored the relationship between APOE genotype and insulin resistance–related damage with respect to BBB integrity, adjusting for vascular and metabolic covariates in a sample of biologically confirmed AD patients." (PMID 39992249, 2025). "According to these data and the large evidence of the role of metabolic syndrome in AD, we hypothesised that insulin resistance might affect BBB integrity synergistically with APOE genotype." (PMID 39992249, 2025). "Therefore, we postulate that both APOE ɛ4 carriers and individuals with high peripheral insulin resistance will need enhanced communication between large-scale brain networks, especially associative networks, to accurately estimate PI." (PMID 39656485, 2024). "Contrary to our initial hypothesis, we found that the effects of APOE ε4 and insulin resistance on PI differed, operating through distinct large-scale network mechanisms." (PMID 39656485, 2024). "Interestingly, a study in human APOE ɛ4-targeted replacement mice has shown that both aging and peripheral insulin resistance induce impairment of brain insulin signaling." (PMID 39656485, 2024). "A study demonstrated that patients, who are ApoE ε4 negative and overweight, are at risk of declined cognitive function due to insulin resistance." (PMID 38441832, 2024). "It has been proposed that the effects of ApoE on inflammation, beta cell function, and insulin resistance may mediate these effects." (PMID 37123009, 2023). "Additionally, TMP can ameliorate insulin resistance and inhibit the expression of Insig-1 in adipose tissue of ApoE-/- mice fed with a high-fat diet." (PMID 35500001, 2022). "What role does apoE genotype really play in both peripheral and/or central insulin resistance?" (PMID 35884888, 2022).